MALRD1 (MAM and LDL receptor class A domain containing 1)
Description:
Enhances production and/or transport of FGF19 and thus has a role in regulation of bile acid synthesis.
Synonyms: C10orf112; DIET1; bA265G8.2
Tractability: Antibody: UniProt predicts a signal peptide or a membrane-spanning region.
Gene: Protein-coding gene on chromosome 10 (19,048,801 to 19,790,401, forward strand). Ensembl gene ENSG00000204740.
Subcellular location: Cytoplasmic vesicle membrane
Subcellular location (Human Protein Atlas): Golgi apparatus
Gene Ontology:
Cellular component: Golgi apparatus; cytoplasmic vesicle membrane; cytoplasm; membrane
Genetic constraint (gnomAD): Loss-of-function variants: 193 observed, 191.56 expected, observed/expected ratio (o/e) 1.01, 90% interval 0.89 to 1.13. The upper end of that interval is the gene's LOEUF score, 1.13, which puts it in group 4 of 6, group 1 being the genes least tolerant of losing a copy. Missense variants: 2,651 observed, 2,324.6 expected, observed/expected ratio (o/e) 1.14, 90% interval 1.1 to 1.18. Synonymous variants: 871 observed, 797.04 expected, observed/expected ratio (o/e) 1.09, 90% interval 1.03 to 1.16.
Homologues: Orthologues: macaque MALRD1 (95% identical), chimpanzee MALRD1 (84% identical), pig MALRD1 (78% identical), rabbit MALRD1 (74% identical), guinea pig MALRD1 (72% identical), mouse Malrd1 (72% identical), rat Malrd1 (71% identical), tropical clawed frog malrd1 (48% identical). Paralogues in human: MAMDC4 (14% identical), MAMDC2 (8% identical), MDGA2 (8% identical), MDGA1 (7% identical).
Diseases named in the same sentence as MALRD1 in open-access papers:
MALRD1 is named in the same sentence as 12 diseases in open-access papers, as found by Europe PMC text mining. Sharing a sentence is not in itself a finding about the gene and the disease. The quoted sentences say what the papers report.
diabetes (1 paper, 2018). "A trend towards association was also detected at two SNPs reported in the only other reported GWAS of DR in Caucasians; rs12267418 near MALRD1 (p = 0.008) in the DME cohort and rs16999051 in the diabetes gene PCSK2 (p = 0.007) in the PDR cohort." (PMID 29739359, 2018).
diabetic macular edema (1 paper, 2024). "Moreover, a genome-wide association study in white Australians with type 2 diabetes revealed that mutations in MALRD1 (rs12267418) were significantly associated with diabetic macular edema." (PMID 39596516, 2024).
hepatocellular carcinoma (1 paper, 2021). A malignant tumor that arises from hepatocytes. "A genetic analysis of patients with hepatocellular carcinoma found MALRD1 (DIET1) to be a co-expressing protein coding gene (PCG) for a long non-coding RNA sequence associated with hepatocellular carcinoma." (PMID 35116006, 2021).
liver fibrosis (1 paper, 2026). "Since we observed a higher incidence of hepatic fibrosis and activation of the hepatic fibrosis signaling pathway in the livers of Malrd1 KO mice, we investigated the presence of MALRD1 in HSCs, a key player in the development of TGFβ-driven hepatic fibrosis." (PMID 41551663, 2026). "The liver RNASeq data showed increased expression of genes (Fold change > 1.5) involved in hepatic fibrosis and HSC activation in Malrd1 KO mice (Figure A2A and B)." (PMID 41551663, 2026). "Our findings demonstrate an FGF15/19 independent role of MALRD1 in liver fibrosis, as unlike small intestine-specific Fgf15 knockout mice,9Malrd1 KO mice exhibit an obesogenic phenotype with a higher incidence of advanced liver fibrosis." (PMID 41551663, 2026).
cancer (4 papers, 2020 to 2025). A tumor composed of atypical neoplastic, often pleomorphic cells that invade other tissues. "It was found that deletions in the RAB9BP1, LOC101928523, and MALRD1 genes were associated with non‐cancer patients who had a family history of cancer (FHC)." (PMID 40556338, 2025). "HHIPL2, XPO1, SALRNA1, ZBTB45, ANP32AP1, ACTR3BP5, LOC100129138, GPR45, and CAB39L gene deletions were associated with non-cancer subjects without FCH (p < 0.05), while RAB9BP1, LOC101928523, and MALRD1 gene deletions were related to non-cancer patients with FCH (p < 0.05)." (PMID 33431054, 2021).
tumor (1 paper, 2020). "Except MALRD1, DUXAP8 and the other 9 PCGs were differentially expressed between tumor and non-tumor tissues." (PMID 32922554, 2020).
MALRD1 also shares sentences with these, for which no sentence is quoted: endometriosis (2 papers); meningioma (2); breast carcinoma (1); psychiatric disorder (1); Stroke (1); type 2 diabetes (1).